HSF1 (heat shock transcription factor 1)
Diseases named in the same sentence as HSF1 in open-access papers (continued):
Sharing a sentence is not in itself a finding about the gene and the disease.
tumor (continued). "Since uncontrolled NF-κB expression negatively regulates apoptosis in tumor cells by affecting several anti-apoptotic genes, such as HSF1, HSP70 and several members of the IAP family, we analyzed the effect of triptolide on the expression of several IAP genes." (PMID 24143232, 2013). "Convincing evidence of HSF1 involvement in carcinogenesis has emerged from data gathered from a murine tumor model." (PMID 24165036, 2013). "The effect of HSF1 knockdown on the proliferation of tumor cells was also tested in Hep3B xenograft mouse model." (PMID 23615731, 2013). "HSF1 shRNA alone inhibited tumor growth by 71%, and knockdown was confirmed and NVP-HSP990 alone at tolerated dosage (10mg/kg PO, qw) inhibited tumor growth by 47%." (PMID 23615731, 2013). "HSF1 is involved in tumor initiation, maintenance, and progression by regulating the expression of heat shock proteins." (PMID 22152097, 2011). "These proteins, like e.g. Stat5 or HSF1, help tumor cells to overcome cellular stress which in normal cells would lead to apoptosis." (PMID 22014102, 2011). "To overexpress HSPs in tumor cells, we used a HSF1 mutant with a deletion within the trimerization domain which can constitutively bind and transactivate HSP gene promoter." (PMID 20459615, 2010). "Copy-number changes in the HSF1 gene have previously been observed across tumor types." (PMID 39831777, 2025). "Moreover, the lncRNA inducing MHC‐I and immunogenicity of tumour (LIMIT) enhances tumour immunogenicity by activating the GBP gene cluster, which disrupts the HSF1 association, leading to HSF1‐mediated transcription of MHC‐I machinery." (PMID 40673641, 2025). "In animal models, DTHIB administration inhibited HSF1 activity during tumor growth without causing significant toxicity." (PMID 40675964, 2025). "The target genes of HSF1 vary across different tumor types, and the specific targets of HSF1 in DLBCL remain unclear." (PMID 40675964, 2025). "While HSF1 disruption can reduce tumor growth, it evidently may also induce amyloid formation, potentially providing a tumor-suppressive effect." (PMID 40287736, 2025). "Heat shock proteins (HSPs and HSF1) assist tumor survival under stress and resistance conditions." (PMID 41235005, 2025). "In addition, HSF-1 can also override cell cycle checkpoints, resulting in proliferation, aneuploidy, and enhanced metastasis in tumor cells." (PMID 41375025, 2025). "In addition, the expression of HSF1 was positively correlated with the tumor size and alpha‐fetoprotein (AFP) level." (PMID 39248163, 2024). "Targeting the mechanisms mediated by HSF1 and HSPs could enhance the sensitivity of hypoxic tumor cells to radiotherapy." (PMID 39655194, 2024). "Heat shock transcription factor 1 (HSF1) broadly influences tumour biology." (PMID 39690143, 2024). "Notably, there was an increased tendency toward severe tumor damage induced by mEHT in the mEHT-treated HSF1-KO group (mEHT EV: 74.6 ± 11%; mEHT HSF1-KO: 84.1 ± 10.6%, p = 0.52, ns)." (PMID 38589452, 2024). "In addition, the TCGA data showed augmented expression of HSF1 in all tumor grades compared to normal tissue." (PMID 39243039, 2024). "However, targeting the upstream regulatory factors or signaling pathways of HSF1 for drug screening provides an indirect pharmacological strategy to more easily inhibit the tumor-promoting effect of HSF1." (PMID 39261452, 2024). "We hypothesized that inhibition of the heat shock factor 1 (HSF1) can synergize with mEHT and enhance tumor cell-killing." (PMID 38589452, 2024). "The role of HSF1 and HSPs in tumor autophagy remains a topic of ongoing debate." (PMID 39850800, 2024). "Furthermore, analysis of CPTAC sample data from UALCAN33, 34 demonstrated significantly elevated protein levels of HSF1 in primary tumor tissues compared to normal tissues." (PMID 39248163, 2024).
tumor (continued). "Furthermore, supporting the tumor volume data, tumor mass was reduced by both mEHT and HSF-1 KO; yet, the smallest tumors were observed in the mEHT KO group by the study termination." (PMID 38589452, 2024). "FBXW7, a critical tumor suppressor, ubiquitinates HSF1 and leads to HSF1 degradation." (PMID 39433125, 2024). "Furthermore, the total levels of ULK1 and its phosphorylation by AMPK at Ser555 were documented upon the knockdown of Hsp70 or HSF1 in A549 tumor cells." (PMID 39201776, 2024). "HSF1 is closely related to the regulation of the cell cycle and proliferation of tumor cells." (PMID 39682216, 2024). "Notably, A549kdHSF1 cells did not demonstrate such THP1-dependent resistance, proving that the effect of monocytes to tumor cell resistance is indeed related to HSF1 activity." (PMID 38280079, 2024). "In addition, HSF1 is an essential factor for the survival of normal cells under stress conditions, indicating that any potential inhibitor must be tumor cell-specific." (PMID 39682216, 2024). "Notably, HSF1, HSF2, and HSF4 were upregulated in HCC, KIRP, and COAD, with HSF1 being upregulated in most tumor types." (PMID 39248163, 2024). "The mechanisms whereby HSF1 drives tumor development toward a more hepatocellular-like phenotype remain obscure and could be multiple." (PMID 39243039, 2024). "Additionally, heat shock transcription factor 1 (HSF1) are directly involved in the response of tumor cells to hypoxia and acidosis, and promote resistance to chemotherapy and radiotherapy." (PMID 38778409, 2024). "In addition, HSF1 also enhances CCL20 secretion by tumor cells, facilitating macrophage infiltration." (PMID 39682216, 2024). "HSF1 promotes tumor progression and survival via a variety of methods." (PMID 37958341, 2023). "Thus, we applied the immunofluorescence staining to assess the role of TRPV1 blockade in interfering the intranuclear HSF1 translocation and intracellular HSP70 expression in tumor cells under hyperthermia caused by CuS-NCs." (PMID 37120615, 2023). "In addition to its role in HSP regulation, HSF1 also promotes tumor cell survival and proliferation by activating the expression of genes involved in cell cycle regulation, DNA repair, and angiogenesis." (PMID 37958341, 2023). "In summary, these data indicated that the expression of HSF1 was significantly elevated in HNSCC tumor tissues compared to adjacent paired tissues, and its expression was correlated with lymph nodal metastasis, tumor grade, and USP14 expression in HNSCC patients." (PMID 37686660, 2023). "Indeed, loss of both HSF1 and DYRK2 led to reduced 3D matrigel invasion and tumour burden in both ectopic and orthotopic QNBC tumour xenograft." (PMID 36622366, 2023). "The expression of HSF1 was higher in tumor tissues than in normal tissues from the TCGA database." (PMID 37686660, 2023). "For instance, we found that EV proteins detected in high invasion capacity tumor cell lines may induce HSF1-dependent transactivation." (PMID 37986165, 2023). "Thus, TRPV1 blockade-mediated suppression of HSF1 nuclear translocation is a key process in alleviating tumor matrix in PDAC models." (PMID 37120615, 2023). "The same study suggested that nuclear accumulation of HSF1 may play a role in tumor neoangiogenesis." (PMID 35311075, 2022). "T cells activated by iDCs can produce cytokines which inhibit the expression of HSPs (HSP27, HSP70, HSP90, HSP105 and HSF1), as well as promoting tumor apoptosis and synergistically amplifying the antitumor effect of low temperature photothermal treatment (42–45°C)." (PMID 36304896, 2022). "AKT2 and AKT3 also have pro‐tumour functions but whether HSF1 can be regulated by these isoforms remains unknown." (PMID 35080342, 2022). "Tumor formation by MeWo cells expressing hHSF1-S326A or hHSF1-S419A was significantly less than that by cells expressing wild-type HSF1; importantly, tumor formation by hHSF1-S326A/S419A-expressing cells was markedly less than that by single mutant-expressing cells." (PMID 35906200, 2022).
tumor (continued). "Moreover, it was proved that EMT can be enhanced to boost tumor metastasis by HSF1 combined with LEF1 dependence in BC." (PMID 35964079, 2022). "Given the dual effects on tumor cells and stroma, we asked whether targeting HSF1 would receive a better result." (PMID 36010849, 2022). "In addition, we proved the efficacy of emetine in inhibiting HSF1 activity and the tumor growth of erlotinib-resistant PC9-ErlR cells in a mouse model." (PMID 34203709, 2021). "HSF1 knockdown further enhanced cell death in vitro and inhibited tumor growth in vivo." (PMID 33675143, 2021). "Functions of HSF1 in tumorigenesis involve the regulation of multiple processes including maintenance of homeostasis, inhibition of apoptosis, control of DNA repair, promotion of tumor invasion and regulation of tumor microenvironment." (PMID 34198675, 2021). "HSF1 facilitates the expression of HSPs, and it also supports tumorigenesis and tumor progression." (PMID 34064083, 2021). "HSF1 exerts a pleiotropic effect on malignancy because it may play roles in many aspects of tumor biology, including DNA repair, angiogenesis, and metabolism." (PMID 34239690, 2021). "HSF1 also plays an important role in tumor development, which seriously affects its prognosis." (PMID 34107992, 2021). "Moreover, Nutlin also regulated the tumor-promoting HSF1 targets CDC6, ITGB3BP, RBBP5, BST2, and FBLN1." (PMID 34188043, 2021). "Next, as a first approximation to address if DYRK2 regulates HSF1 in vivo, we asked whether the levels of DYRK2 correlate with HSF1 levels in tumour tissue from TNBC patients." (PMID 33268814, 2021). "Specifically, tumor cells express high levels of HSF1 via a variety of methods, for example, inhibiting the ubiquitinated degradation of HSF1, reducing the expression of molecules that compete with HSF1 and stimulating HSF1 activation-related pathways (such as EGFR mediated MAPK pathway)." (PMID 33422093, 2021). "Moreover, both gene and protein expression levels of HSF1 have also been reported to be elevated in tumor tissues of gastric patients." (PMID 34064083, 2021). "Furthermore, in vivo in heterozygous tumor-bearing p53Q/+ mice, Nutlin induced a moderate RB and HSF1 dephosphorylation." (PMID 34188043, 2021). "HSF1 and HSPs are directly involved in the tumor cell response to hypoxia." (PMID 33806538, 2021). "Finally, it would be desirable to elucidate the mechanisms that allow for the amplification of HSF1 expression and activity in both tumor cells and CAFs." (PMID 32331382, 2020). "HSF1 has been linked with Focal Adhesion Kinase (FAK) activity, and FAK activity is dependent upon Rho/ROCK signaling which influences focal adhesion dynamics and tumor cell migration and invasion." (PMID 32245408, 2020). "In addition, HSF1 inhibition decreased tumor growth and increased the overall survival of tumor-bearing mice." (PMID 31878360, 2019). "Consistent with the DAF-16/FOXO-controlled tumor gene, dct-10, being one of the most robustly induced pseudogenes, we found that its promoter contains multiple HSEs and its expression in HS is regulated by hsf-1." (PMID 31396626, 2019). "Furthermore, in a xenograft model of breast cancer a simultaneous targeting of Akt and HSF1 significantly reduced tumor growth, delayed outcome of metastasis, and prolonged the host survival." (PMID 31652993, 2019). "Our results suggest that HSF1-dependent DKK3 upregulation could be a response of stromal fibroblasts to stresses found in the tumour microenvironment." (PMID 30631061, 2019).
tumor (continued). "Furthermore, HSF1 activity strongly correlated with DKK3 gene expression in the stromal compartment of human tumours." (PMID 30631061, 2019). "Mechanistically, tumor cells respond to many kinds of stresses with the activation of heat-shock factor 1 (HSF1), the master transcription factor for all stress-induced heat-shock proteins which include Hsp90α, Hsp70, members of the HSP40/DNAJ family, and numerous co-chaperones." (PMID 29875343, 2018). "Moreover, the expression of miR-644a was negatively correlated with HSF1 expression (P = 0.004), tumour diameter (P = 0.001) and TNM stage (P = 0.001)." (PMID 29898735, 2018). "Moreover, a high HSF1 level in tumour tissues serves as a poor prognosis predictor in patients with carcinoma." (PMID 30326922, 2018). "Recent studies have reported that HSF1 can act as an oncogene that regulates tumour progression." (PMID 30326922, 2018). "There is a general consensus among scientists working in the field that discovering a potent and selective inhibitor of HSF-1 could be very valuable to suppress carcinogenesis and tumor growth." (PMID 29682483, 2018). "Finally, in nude mice HCT-116 cells xenograft model, vitexin resulted in repression of tumor growth suggesting HSF-1 as potential therapeutic target." (PMID 29348836, 2017). "Furthermore, human tumor cells from different sources have been shown to be more dependent on HSF1 than normal cells in maintaining cell growth and proliferation." (PMID 28482903, 2017). "Of note, we found that HSF1 was strongly upregulated in c-Myc tumor samples." (PMID 29207593, 2017). "Unlike normal cells, tumor cells are characterized by a permanently high rate of protein misfolding due to abundance of mutated oncoproteins, making HSF1 ubiquitously and constitutively overexpressed." (PMID 27791982, 2017). "As we recently showed that HSF1 depletion suppresses liver tumor development induced by the AKT protooncogene, the present evidence suggests that HSF1 might support liver malignant transformation and tumor progression driven by various oncogenes." (PMID 29207593, 2017). "As the activation of the master regulator HSF1 varies among different primary tumor sites, HSF1-CanSig 8q genes may be developed as prognosis biomarkers for improving clinical outcomes." (PMID 29268782, 2017). "Furthermore, we examined the distribution of HSF1-CanSig 8q genes by individual primary tumor sites." (PMID 29268782, 2017). "Therefore, as a tumor regulator, HSF1 plays a key regulatory role in inhibiting tumor cell apoptosis and promoting tumor development." (PMID 28482903, 2017). "The tumor initiating population has also been defined as CD44highCD24lowESAhigh, so we next determined whether inhibition of HSF1 had an effect on this population." (PMID 29088759, 2017). "Consequently, this drives the overexpression of the HSF1-CanSig in tumor cells and possibly the surrounding stroma leading to metastasis and poor clinical outcomes." (PMID 29268782, 2017). "Furthermore, HSF1 has been found to be a downstream effector of the mammalian target of rapamycin (mTOR) pathway in this tumor type." (PMID 28903330, 2017). "Moreover, HSF1 expression also correlates with metastasis and poor survival rate in endometrial cancer, and tumor size in oral squamous cell carcinoma (OSCC)." (PMID 28914774, 2017). "However, only when KRIBB11 was combined with MK-2206 did we observe significant decreases in tumor volume and expression of HSF1 target genes." (PMID 29088759, 2017). "In these tumor cells, HSF1 and PARP1 formed a complex in a manner dependent on PARP13." (PMID 29158484, 2017). "Clustered HSF1-CanSig 8q genes co-express at a high level in several primary tumor sites." (PMID 29268782, 2017).
tumor (continued). "HSF1 has also been shown to transactivate a variety of genes involved in tumor progression." (PMID 26754925, 2016). "In addition, studies of HSF-1 show the positive correlation between HSF-1 and tumor malignancy, and silencing HSF-1 increases antitumor activity of HSP90 inhibitor." (PMID 27105490, 2016). "HSF1 may also play these roles in ESCC and thus account for high levels of HSF1 expression in the nucleus of ESCC tumor cells associated with patients’ poor outcomes." (PMID 26511079, 2015). "Additionally, the expression of HSF1 in tumor cells or stromal cells was an independent factor for DFS (P = 0.032 or P = 0.012) and OS (P = 0.017 or P = 0.013) in metastatic ESCC patients but not for locoregional ESCC." (PMID 26511079, 2015). "Furthermore, we revealed that HSF1 is located in the nucleus and cytoplasm of both tumor cells and stromal cells close to malignant cells in the human ESCC tissues." (PMID 26511079, 2015). "Because of the limited expression profile of PKCθ to some solid tumors and immune cells, and the fact that HSF1 is often overexpressed in tumors, TZL might only be lethal to PKCθ-expressing, HSF1- addicted glycolytic tumor cells." (PMID 26298773, 2015). "The expression of HSF1 in tumor was the same as the expression in normal tissue in only one case." (PMID 26511079, 2015). "HSF1 may play an important role in tumor initiation, development and maintenance, and activation of HSF1 contributes to resistance to Hsp90 inhibitors." (PMID 26416354, 2015). "HSF1 activation in stromal cells plays a more significant role in the tumor progression or migration and thus may be a better predictor for ESCC patients’ prognosis." (PMID 26511079, 2015). "However, the reduction in NK cell-mediated lysis was much more pronounced after treatment of the H1339 tumor cells with NZ28 compared to that of a HSF1 knockdown." (PMID 25854583, 2015). "The cooperation between HSF1 activation in stromal cells and tumor cells may promote tumor development." (PMID 26511079, 2015). "HSF1 is overexpressed in a broad range of tumors and tumor cell lines." (PMID 24467529, 2014). "Since HSF1 plays a vital role in cytoprotection from high temperatures, acidosis, and neurodegenerative disorders, its therapeutic inhibition must be limited exclusively to the tumor area." (PMID 24467529, 2014). "Heat shock-activated HSF1 is mainly responsive to the expression of heat shock proteins, while activation of HSF1 in tumor tissues is predominantly responsible for controlling the expression of non-heat shock proteins, e.g. CKS2, LY6K, RBM23, CCT6A, CKS1B, ST13 and EIF4A2." (PMID 25199534, 2014). "Hence, HSF1 play a crucial role in regulation of the level of HSPs, which is regulated by some of tumor-related genes and proteins." (PMID 25147790, 2014). "HSF1 staining was then scored in 50 human HCC tumor samples." (PMID 23615731, 2013). "More strikingly, HSF1 knockdown & NVP-HSP990 combination led to 76% tumor regression." (PMID 23615731, 2013). "HSF1 shRNA alone inhibited tumor growth by 53% T/C, and knockdown was confirmed." (PMID 23615731, 2013). "HSF1 mRNA was significantly elevated in HCC tumor in compared to normal control." (PMID 23615731, 2013). "Due to the important roles of heat shock proteins (HSPs) in eliciting innate and adaptive immunity, we reasoned that besides increasing the viral burst, HSF1 may also play a role in increasing tumor specific immune response." (PMID 22613625, 2012). "Our previous study showed that heat shock transcription factor 1 (HSF1) overexpression could increase the anti-tumor efficacy of E1B55kD deleted oncolytic adenovirus through increasing the viral burst." (PMID 22613625, 2012).